MYBL2 (MYB proto-oncogene like 2)
Diseases named in the same sentence as MYBL2 in open-access papers (continued):
Sharing a sentence is not in itself a finding about the gene and the disease.
acute myeloid leukemia (8 papers, 2013 to 2024). Acute myeloid leukemia (AML) is a group of neoplasms arising from precursor cells committed to the myeloid cell-line differentiation. "For example, circ-MYBL2, a circRNA from MYBL2 gene, is reported to facilitate the progression of acute myeloid leukemia by regulating fms-related receptor tyrosine kinase 3 (FLT3) translation through recruiting polypyrimidine tract binding protein 1 (PTBP1)." (PMID 38165465, 2024). "Previous analyses also suggested a modified presence of circ-MYBL2, a circRNA originating from MYBL2, in acute myeloid leukemia and cervical tumors." (PMID 35406472, 2022). "Both of these miRNAs target MYBL2, with aberrant expression of mir-29a leading to clonal dominance and acute myeloid leukemia." (PMID 23878725, 2013). "We used PCR-generated small CRISPR constructs to edit two genes (IDH2 and MYBL2) in hard-to-transfect hemopoietic cells, which are central to the progression of the devastating disease known as acute myeloid leukemia LMA (AML)." (PMID 37686539, 2023).
bladder cancer (8 papers, 2019 to 2025). "In vitro study had also suggested a close association between MYBL2 with bladder cancer cells's metastasis and proliferation, and inhibiting MYBL2 can substantially reduce proliferation and metastasis." (PMID 38961953, 2024). "The area under the curve (AUC) values for circ_0006332 and MYBL2 were 0.860 and 0.885, respectively, thereby demonstrating their potential as early diagnostic markers for bladder cancer." (PMID 31756170, 2019). "Previous studies have shown that the transcription factor MYBL plays a role in the growth and spread of bladder cancer, while reducing MYBL2 levels effectively inhibits the proliferation and spread of bladder cancer cells, resulting in a halt in the G2 phase." (PMID 39136009, 2024). "Specifically, MYBL2 contributes to the proliferation and metastasis of bladder cancer by upregulating the expression of cell division cycle-associated protein 3 (CDCA3)." (PMID 38725627, 2024). "We demonstrated that circ_0006332 increases MYBL2 levels in bladder cancer tissues and cell lines by sponging miRNA-143." (PMID 31756170, 2019). "Sequencing analysis showed that circ_0006332 is generated by splicing within the MYBL2 transcript and significantly upregulated in bladder cancer tissues." (PMID 31756170, 2019). "Our data also shows that circ_0006332 promotes bladder cancer cell proliferation and invasion, and regulates MYBL2 expression." (PMID 31756170, 2019). "Overall, our data suggests that circ_0006332 increases MYBL2 protein levels by sponging miR-143 in bladder cancer tissues and cell lines." (PMID 31756170, 2019). "QRT-PCR showed that the expression of circ_0006332 positively correlated with the expression of MYBL2 in both bladder cancer tissues and 6 cell lines including 5637, T24, J82, UM-UC-3, TSCCUP and SV-HUC-1." (PMID 31756170, 2019). "We further observed significantly lower MYBL2 protein levels in xenograft tumors derived from circ_0006332 knockdown bladder cancer cells compared with the controls." (PMID 31756170, 2019). "In conclusion, our study demonstrates that circ_0006332 increases MYBL2 expression by acting as a sponge for miR-143, and promotes the proliferation and invasion of bladder cancer." (PMID 31756170, 2019). "This suggests that circ_0006332 increases RNA expression of MYBL2 by sponging miR-143 in the bladder cancer cells." (PMID 31756170, 2019). "Our study demonstrates that circ_0006332 promotes the growth and progression of bladder cancer by modulating MYBL2 expression by acting as a sponge for miR-143." (PMID 31756170, 2019). "Circ_0006332 knockdown by siRNA significantly decreased the expression of MYBL2, whereas, overexpression of circ_0006332 significantly increased the expression of MYBL2 in the bladder cancer cell lines T24 and UM-UC-3." (PMID 31756170, 2019). "MYBL2 expression was unchanged in bladder cancer cells after transfection with siRNA-1 and siRNA-2." (PMID 31756170, 2019). "Our results show that MYBL2 is significantly overexpressed in bladder cancer cells and tissues." (PMID 31756170, 2019). "Similarly, MYBL2 mRNA levels were significantly higher in the bladder cancer tissues compared with the adjacent normal bladder tissues." (PMID 31756170, 2019). "Moreover, circ_0006332 levels positively correlate with MYBL2 expression in the bladder cancer tissues and cells." (PMID 31756170, 2019). "The top five pathways following MYBL2 treatment included pathways in cancer, small cell lung cancer, PI3K-Akt signaling pathway, bladder cancer, and inflammatory bowel disease (IBD)." (PMID 35664780, 2022). "The circRNA transcripts of the MYB Proto-Oncogene Like 2 (MYBL2) and Cyclin B1 (CCNB1) genes were significantly upregulated in the bladder cancer tissue samples." (PMID 31756170, 2019).
endometrial cancer (8 papers, 2015 to 2025). Primary or metastatic malignant neoplasm involving the endometrium (mucous membrane that lines the endometrial cavity). "Therefore, MYBL2 could serve as a prognostic marker for endometrial cancer and is associated with disease stage and survival outcomes." (PMID 40432915, 2025). "According to the Receiver Operating Characteristic (ROC) curve analysis, MYBL2 demonstrated excellent accuracy in predicting the prognosis of endometrial cancer patients." (PMID 40432915, 2025). "Compared to the control group, the expression of MYBL2 was upregulated in endometrial carcinoma, whereas CPEB1 expression was downregulated." (PMID 38994352, 2024). "ERβ expression is positively correlated with MYBL2 expression in endometrial cancer tissues, which supports a relationship between the increased risk of endometrial cancer and MYBL2 expression levels in premenopausal women." (PMID 37144133, 2023). "Recent studies have also shown that MYBL2 is significantly upregulated in endometrial cancer (E.C.)and esophageal squamous cell carcinoma (ESCC), accompanied by significant copy number changes (CNA)." (PMID 35664326, 2022). "This strong association of expression of E2F1, E2F2 and MYBL2 with ATAD2 is found in both CAHs, primary and metastatic endometrial cancer lesions, indicating that the expression of these genes are tightly linked in all stages of endometrial cancer." (PMID 26308378, 2015). "In 2015, a study observed that the expressions of E2F transcription factor 1 (E2F1), E2F transcription factor 2 (E2F2), and MYB proto-oncogene like 2 (MYBL2) are closely associated with ATAD2, which may be related to the invasion and progression of endometrial cancer." (PMID 36479043, 2022). "This same pattern is also observed for E2F1 and MYBL2, located close to the region 20q13 often amplified in the serous like molecular sub group of endometrial cancer, indicating that in addition to a transcriptional link, these genes may also be co-amplified due to general genomic instability." (PMID 26308378, 2015). "Survival analyses from the Kaplan-Meier Plotter database revealed a significant decrease in OS of patients with endometrial carcinoma as the expression levels of CPEB1 and MYBL2 increased." (PMID 38994352, 2024).
COVID-19 (6 papers, 2022 to 2024). A disease caused by infection with severe acute respiratory syndrome coronavirus 2. "ZNF385D and MYBL2 were both listed as hub genes in a study examining the influence of COVID-19 on ischemic stroke." (PMID 38674024, 2024). "MYBL2 was listed in the context of neutrophil degranulation during COVID-19, while ZNF385D was identified in an epigenome-wide association study (EPICOVID)." (PMID 38674024, 2024). "Mesenchymal stem cells (MSCs) induced and upregulated MYBL2 gene was present in all infected COVID-19 groups." (PMID 35983322, 2022). "ACE (AUC: 0.923), CYP1A1 (AUC: 0.902), EME1 (AUC: 0.977), CD52 (AUC: 0.970), MYBL2 (AUC: 0.995), CDC25A (AUC: 0.998), BCL6 (AUC: 0.966) and CD3D (AUC: 0.955) showed relatively good diagnostic efficiency in distinguishing COVID-19 patients from healthy controls." (PMID 38978778, 2024). "CDC25A, GUSB, MYBL2, and SDAD1 were identified as key genes in severe COVID-19." (PMID 35887528, 2022). "Finally, we evaluate the limited but non-zero effect of COVID-19 phenotype on eQTL discovery, and highlight the presence of COVID-19 severity-interaction eQTLs (ieQTLs; e.g., CLEC4C and MYBL2)." (PMID 35995775, 2022).
melanoma (6 papers, 2018 to 2024). A malignant, usually aggressive tumor composed of atypical, neoplastic melanocytes. "Investigating the effects of MYB proto-oncogene like 2 (MYBL2)-mediated regulation of Cell division cycle associated 8 (CDCA8) expression on the biological activity of cutaneous malignant melanoma cells." (PMID 38961953, 2024). "We arrived at such a conclusion that MYBL2 promoted the migration, invasion and proliferation ability of cutaneous malignant melanoma cells by targeted regulation of CDCA8 expression in this study." (PMID 38961953, 2024). "To investigate the regulatory mechanism of MYBL2 on CDCA8 expression in human malignant melanoma cells, we transfected MYBL2, CDCA8 genes, and their co-overexpression and knockdown plasmids into A375 cells." (PMID 38961953, 2024). "In summary, our research reveals the overexpression of MYBL2 in malignant melanoma cells, which promotes the migration, invasion and proliferation abilities of these cells." (PMID 38961953, 2024). "MYBL2 was expressed in all the tested cell lines, and higher expression level was observed in melanoma cell lines (A375, SK-MEL-28, and A2058) than in melanocytes (HEMn-LP)." (PMID 35664780, 2022). "According to MYBL2 expression levels, 455 melanoma patient samples were allocated into low- and high-MYBL2-expressing groups." (PMID 35664780, 2022). "Kaplan–Meier analysis based on TCGA data revealed that high MYBL2 expression level was positively correlated with poorer progression-free survival of melanoma patients in the cohort of cutaneous melanoma (p = 0.0141)." (PMID 35664780, 2022). "Further study surrounding the mechanisms involving MYBL2 in melanoma by cytological functional testing is helpful to explain the expression of MYBL2 in tissues." (PMID 35664780, 2022). "In conclusion, by analyzing the expression and prognostic value of MYBL2 in melanoma through multi-platform data integration, we determined that melanoma has the characteristics of typical MYBL2-dependent tumors." (PMID 35664780, 2022). "Mechanistically, we constructed an MYBL2 regulatory network in melanoma by integrating RNA-seq and ChIP-seq data." (PMID 35664780, 2022). "In the control group, the expression level of MYBL2 was low; in the malignant melanoma group, the degree of MYBL2 IHC staining was significantly increased, and most samples exhibited moderate positivity." (PMID 35664780, 2022). "To evaluate the stemness of MYBL2-expressing melanoma cells, we downloaded and converted melanoma RNA-Seq (FPKM) data to TPM and normalized the data log2 (TPM+1), while keeping samples with clinical information recorded." (PMID 35664780, 2022). "The Kaplan–Meier survival plot was grouped by the median MYBL2 expression level in melanoma samples." (PMID 35664780, 2022). "The expression of MYBL2 was also detected in human melanocytes (HEMn-LP), human malignant melanoma cell lines (A375 and SK-MEL-28), and metastatic melanoma cell lines (A2058) by Western blotting." (PMID 35664780, 2022). "In the present study, we aimed to determine the oncogenic role of MYBL2 and characterize MYBL2-mediated regulatory networks/direct targets in melanoma." (PMID 35664780, 2022). "Next, 11 core target genes of MYBL2 were identified by integrating RNA-seq and ChIP-seq data, suggesting that MYBL2 promoted melanoma growth." (PMID 35664780, 2022). "In our study, we determined that MYBL2 KD decreased the proportion of cells in the G1 phase and induced G2 phase arrest in human melanoma A375 and A2058 cell lines." (PMID 35664780, 2022). "Taken together, this evidence indicated that MYBL2 was involved in cell proliferation and tumorigenesis in melanoma, which is consistent with our present findings." (PMID 35991567, 2022). "Our results indicated that MYBL2 was highly expressed in melanoma samples, revealing a poor prognosis in patients with melanoma." (PMID 35664780, 2022).
melanoma (continued). "We also determined that MYBL2 promoted the formation of melanoma stem-like cell populations, indicating its potential as a therapeutic target for treating resistant melanoma." (PMID 35664780, 2022). "Through integrated RNA sequencing, target prediction, and functional assays, we identified the transcription factors MAFG and MYBL2 as bona fide miR-29 targets in melanoma." (PMID 33808771, 2021). "MYBL2 has oncogenic properties in breast, lung, colorectal and other cancers, and our findings suggest a role for MYBL2 also in melanoma." (PMID 33808771, 2021). "MYBL2 has been described as a target of miR-29 during senescence of HeLa cells, and we confirmed that miR-29 represses MYBL2 also in melanoma cells." (PMID 33808771, 2021). "Future studies will address if overexpression of MAFG or MYBL2 contributes to melanocyte transformation and melanoma development." (PMID 33808771, 2021). "We further identify the transcription factors MAFG and MYBL2 as targets of miR-29 and show that their repression is detrimental for melanoma cells." (PMID 33808771, 2021). "In conclusion, these results illustrated a strong association between MYBL2 expression level and reduced survival in melanoma patients, and suggested that MYBL2 may be a useful biomarker for patient diagnosis and prognosis in melanoma cases." (PMID 35664780, 2022). "Silencing of MYBL2 obviously inhibited the proliferation of melanoma cells compared to the control." (PMID 35664780, 2022). "Overall, our findings elucidate an MYBL2 regulatory network related to cell proliferation and cancer development in melanoma, suggesting that MYBL2 may be potentially targeted for melanoma diagnosis and treatment." (PMID 35664780, 2022). "In a subsequent in vitro mechanism study, we determined that shRNA lentivirus-mediated MYBL2 reduction could inhibit the proliferation, metastasis, and cycle arrest of melanoma cells." (PMID 35664780, 2022). "KEGG pathway analysis was performed to detect MYBL2 gene expression in melanoma cells." (PMID 35664780, 2022). "We next sought to validate MAFG and MYBL2 as targets of miR-29 in melanoma." (PMID 33808771, 2021). "Knockdown of MAFG and, to a lesser extent, MYBL2 significantly decreased proliferation and focus formation of A375 melanoma cells, suggesting that miR-29 may suppress melanoma by targeting these two genes." (PMID 33808771, 2021). "Targeting MAFG- and MYBL2-regulated processes may therefore represent a promising therapeutic strategy to treat miR-29-low melanoma." (PMID 33808771, 2021). "De-repression of MAFG and MYBL2, which we identified as bona fide targets of miR-29, may contribute to melanoma development." (PMID 33808771, 2021). "MYBL2 may be a potential target for the diagnosis and treatment of melanoma." (PMID 35664780, 2022). "Moreover, we determined that MYBL2 promoted the growth of melanoma cells and melanoma stem-like cell proliferation in a mouse model and in melanoma cells, indicating that MYBL2 may be used as a biomarker or therapeutic target." (PMID 35664780, 2022). "However, we need to further explore how MYBL2 affects the proliferation of melanoma cells." (PMID 35664780, 2022). "We further explored whether MYBL2 affects melanoma growth in vivo." (PMID 35664780, 2022). "Finally, we identified MAFG and MYBL2 as miR-29 targets whose de-repression may be critical for melanoma development." (PMID 33808771, 2021). "To determine pairwise correlations involving MYBL2 expression and three genes (FCGR2A, PDE3A, and EPPK1), we reanalyzed the transcriptome data of melanoma cases from TCGA." (PMID 35664780, 2022). "Moreover, MYBL2 and its downstream transcriptional network can provide effective targets for tumor therapy, and it may be used as a biomarker for the diagnosis and prognosis of melanoma." (PMID 35664780, 2022). "Our work uncovered that miR-29 constrains MAPK pathway-driven melanoma formation, at least in part, by repressing MAFG and MYBL2." (PMID 33808771, 2021).
melanoma (continued). "Our findings suggest that attenuation of miR-29b2~c expression promotes melanoma development, at least in part, by derepressing MAFG and MYBL2." (PMID 33808771, 2021). "Together with the outcomes of the in vitro experiments, these findings validate a direct association between MYBL2 and CDCA8 expression in the advancement of malignant melanoma cell proliferation and migration, and CDCA8 could be directly transcriptionally regulated by MYBL2." (PMID 38961953, 2024). "Therefore, our in vivo validation that miR-29 is a tumor suppressive miRNA in melanoma might contribute to the development of new therapeutic approaches, not only targeting MAFG or MYBL2, but also miR-29 itself." (PMID 33808771, 2021).
glioblastoma (5 papers, 2013 to 2022). The most malignant astrocytic tumor (WHO grade IV). "In the case of MYBL2, this may be due to EGFR signaling, which is frequently amplified and overexpressed in IDH-wildtype glioblastomas and was reported to activate the MYBL2 promoter in association with E2F1." (PMID 35228525, 2022). "In contrast, transient knock-down of either ETS1 or MYBL2 resulted in a significant decrease of 4EBP1 mRNA and protein levels in both glioblastoma cell lines." (PMID 35228525, 2022). "Each of these transcription factors harbors oncogenic or tumor-promoting functions and some of them were reported to be overexpressed in cancer, including overexpression of E2F1, E2F6, FOXM1, and MYBL2 in glioblastomas." (PMID 35228525, 2022). "We showed with promoter-reporter assays and genetic knockdown experiments that among these factors, ETS1 and MYBL2 regulate EIF4EBP1 transcription in IDH-wildtype glioblastoma cells." (PMID 35228525, 2022). "Taken together, this raises the possibility that the induction of EIF4EBP1 expression by ETS1 and MYBL2 in glioblastoma cells may be a previously unrecognized mechanism mediating angiogenesis in this tumor type." (PMID 35228525, 2022). "Independently of ETS1 or MYBL2, 4EBP1 may exhibit other functions in glioblastomas." (PMID 35228525, 2022). "Based on these results, we identified two transcription factors, ETS1 and MYBL2, that regulate EIF4EBP1 expression in glioblastoma cells." (PMID 35228525, 2022). "In summary, we elucidated molecular mechanisms of enhanced EIF4EBP1 levels in glioblastoma cells, revealing the oncogenic transcription factors ETS1 and MYBL2 as responsible transcriptional regulators." (PMID 35228525, 2022). "The co-expression of MYBL2 and FoxM1 was analyzed in low-grade glioma (LGG) and glioblastoma (HGG) cohorts of TCGA using cBioportal and UCSC Xena." (PMID 28784180, 2017). "These analyses indicate that the co-expression between MYBL2 and EIF4EBP1 is not restricted to glioblastomas, suggesting that MYBL2 might represent a more general regulatory mechanism driving EIF4EBP1 expression in different cancer entities." (PMID 35228525, 2022).
lymph node metastasis (5 papers, 2017 to 2024). "Furthermore, a recent study using only clinical samples showed that higher levels of MYBL2 were associated with poor prognosis, poor differentiation, and lymph node metastasis, suggesting that MYBL2 may have an oncogenic function in GC." (PMID 39613162, 2024). "In addition, we found that rs405660 was significantly associated with a decreased risk of lymph node metastasis in TNBC, and this finding may provide a reference for subsequent clinicopathological studies on MYBL2 in association with TNBC." (PMID 37144133, 2023).